MDM2 (MDM2 proto-oncogene)
Diseases named in the same sentence as MDM2 in open-access papers (continued):
Sharing a sentence is not in itself a finding about the gene and the disease.
tumor (continued). "FISH studies demonstrated that the tumor was negative for amplification of MDM2 and rearrangements of EWSR1, FUS, and KMT2A." (PMID 34592995, 2021). "Currently, MDM2 gene amplification and/or protein overexpression in human cancers are assessed by ex vivo methods, such as fluorescence in-situ hybridization (FISH) and immunohistochemical (IHC) staining of tumor biopsy material." (PMID 33924734, 2021). "Conclusion: hsa_circ_0000073 functions as a tumor promoter in OS to increase malignant tumor behavior through sponging miR-1252-5p and regulating CCNE2 and MDM2 expression, which could be a novel target for OS therapy." (PMID 34568326, 2021). "In addition to an MDM2 amplification, copy number analyses also revealed amplification of CDK4 in three tumors (cases 1–3) and a deletion of CDKN2A in one tumor (case 5)." (PMID 32352245, 2020). "CD44 is required for Mdm2 nuclear translocation and AKT activation leading to tumor progression." (PMID 32984031, 2020). "As increased MDM2 expression suppresses GPRC5A, a tumor suppressor gene in A549 cells, our data might suggest that phenanthriplatin treatment could reduce MDM2 and thereby nullify the effect of GPRC5A to suppress tumor progression." (PMID 33302475, 2020). "It is known that the products of MDM2 gene play an important role in HCC and promote tumor growth." (PMID 33173438, 2020). "Third, the binding of pRb to other proteins, such as MDM2, or certain DNA viral oncoproteins (hr-HPV E7 oncoprotein) may also override the tumor suppressor function of pRb." (PMID 35047986, 2020).
tumor (continued). "The immunohistochemical analyses performed on the tumor with total excision revealed negative staining for MDM2 and CDK4." (PMID 31282548, 2020). "This miRNA suppressed CSC properties, possessed various anti-tumour effects against CRC cell lines and CRC cell cultures derived from clinical CRC samples through direct inhibition of KLF5 and MDM2, and provoked G1 arrest via direct inhibition of TFDP1, which forms a heterodimer with E2F1." (PMID 32066912, 2020). "This MDM2 DNA could be transferred to preadipocytes (P-a), a major and ubiquitous cellular component of the DDLPS tumor microenvironment (TME), with subsequent P-a production of matrix metalloproteinase 2 (MMP2), a critical component in the metastatic cascade." (PMID 32258243, 2020). "We assume also that the non-cancer cells adjacent to the tumor receive a lower irradiation dose and a lower effective dose of the Mdm2 inhibitor." (PMID 32724100, 2020). "Then, we examined the expression of MDM2 and USP7 in MDA-MB-468 xenograft tumor samples." (PMID 32929379, 2020). "By immunohistochemistry, tumor cells demonstrated strong nuclear cyclin D1 expression and multifocal smooth muscle actin staining but were negative for MUC4, ERG, CD34, S-100 protein, desmin, STAT6, CD45, MDM2, CDK4, ALK, and ROS1." (PMID 32461620, 2020).
tumor (continued). "Among these genes, CCND1 and MDM2 are known to be oncogenes and CDKN2A is a tumor suppressor." (PMID 30755618, 2019). "While MDM2 has previously been implicated in driving BC metastasis, information about the role of MDMX in driving circulating tumor cells (CTCs) and BC metastasis is lacking." (PMID 31489110, 2019). "Additionally, MDM2 prevents the localization of the repressor element-1 silencing transcription factor (REST), a tumor suppressor that downregulates PI3-kinase activity and Akt phosphorylation on the p85 promoter." (PMID 31416195, 2019). "Similarly, synergistic efficacy was observed in combination treatment with another MDM2 inhibitor BI907828 and anti-PD-1 antibody in a syngeneic tumor model." (PMID 31779710, 2019). "In addition, analyzing another publicly available CRPC dataset (GEO dataset number GSE35988), we found that more MDM2 and MDMX co-amplification in metastatic CRPC patient samples comparing to benign or local tumor samples." (PMID 29464071, 2018). "There is increasing evidence suggesting that mouse double minute 2 homolog (MDM2), insulin-like growth factor 1 (IGF1), signal transducer and activator of transcription 1 (STAT1), and Rac family small GTPase 1 (RAC1) are involved in tumor progression." (PMID 29651441, 2018). "Furthermore, low levels of stromal TRIM28 correlated with elevated MDM2 levels in tumor epithelium (p = 0.01) and COX-2 levels in tumor stroma (p = 0.002)." (PMID 29631612, 2018). "MDM2 and VEGF are important molecules involved in tumor progression." (PMID 28274247, 2017).
tumor (continued). "In addition, exogenous HBx expression enhanced the capacity of tumor sphere formation in OV6+ HCC cells, whereas downregulation of MDM2 abolished this effect." (PMID 28102846, 2017). "It acts as a tumor suppressor in normal growth conditions by inhibiting PTEN through miR-17-5p and at unfavorable conditions miR-17-3p promotes tumor cell survival by inhibiting MDM2." (PMID 29050357, 2017). "Given the observed inhibitory effect of gossypol on MDM2 and VEGF expression and cancer cell apoptosis, we investigated whether gossypol could suppress tumor growth and VEGF-mediated angiogenesis in a nude mouse xenograft model." (PMID 28274247, 2017). "MDM2 acts as an oncoprotein, while VEGF plays crucial roles in tumor angiogenesis." (PMID 28274247, 2017). "At the molecular level, the pharmacological treatment was able to induce upregulation of MDM2 and P21 in all cancer cell lines and PUMA expression was correlated with apoptosis induction and tumor regression suggesting a direct role in mediating SAR405838 biological effects." (PMID 28673313, 2017). "Through disrupting the interaction between MDM2 protein and VEGF mRNA, gossypol induces MDM2 self-ubiquitination and decreases VEGF translation simultaneously, which results in not only cancer cell apoptosis but also suppression of tumor angiogenesis." (PMID 28274247, 2017). "Particularly, proliferative targets of MDM2 include the stimulation of E2F1 transcriptional activity, increased E2F1 protein stability, disruption of the Rb-E2F1 complex and inhibition of tumor suppressive functions of Rb." (PMID 28615518, 2017). "SAR405838 promoted complete tumor regression after oral administration of 200 mg/kg/wk, whereas other potent MDM2-inhibitors (RG7112 and RG7388) did not achieve this effect." (PMID 27888811, 2017).
tumor (continued). "Tumor cells were treated with triptolide and doxorubicin, either in the presence or absence of ectopic expression of MDM2." (PMID 27004407, 2016). "In summary, 136 miRNAs significantly differentially expressed in MDM2-positive and -negative tumours were identified." (PMID 26918730, 2016). "However, these molecules are only active against MDM2, and some authors have argued that dual inhibitors of MDM2 and MDMX are needed to expand the range of tumours that can be treated." (PMID 26936767, 2016). "In this therapeutic approach, the determinants of differential tumor response would be defined by the sensitivity of each cancer to the mitotic inhibitor, rather than to the MDM2 inhibitor." (PMID 25730903, 2015).